ABCG2 (ATP binding cassette subfamily G member 2 (JR blood group))
Diseases named in the same sentence as ABCG2 in open-access papers (continued):
Sharing a sentence is not in itself a finding about the gene and the disease.
breast cancer (continued). "Moreover, we discovered that KRT19 regulates CSC reprogramming and drug sensitivity in breast cancer and cancer stem cell-like cells, through mediating stemness (NANOG, OCT4, KLF4, and SOX2) and drug-resistant (ALDH1, ABCG2, ABCC1, and ABCB1) marker expression." (PMID 29747452, 2018). "In addition, in the triple negative (basal-type) breast cancer cell line MDA-MB-231, which shows low expression of endogenous ABCG2, an inverse correlation between ENPP1 and miR-27b expression was observed, although the cell surface localization of ABCG2 was not induced by knockdown of miR-27b." (PMID 26065921, 2015). "However, work with prostate and breast cancer cells shows that ABCG2-positive and -negative cells have similar tumorigenicity." (PMID 21917149, 2011). "Interestingly, one smaller study with 59 primary breast cancer patients reported a negative correlation between ABCG2 mRNA expression and response rate and progression-free survival with anthracycline-based chemotherapy." (PMID 18382425, 2008). "The main efflux transporters involved in BC MDR are ABCB1 (also termed P-glycoprotein, P-gp, or MDR1), multidrug resistance protein 1 (MRP1/ABCC1) and ABCG2 (also termed breast cancer resistance protein BCRP or mitoxantrone resistance protein MXR)." (PMID 38877575, 2024). "Asperjinone, a nor-neolignan, and Terrein, a suppressor of ABCG2-expressing breast cancer cells were isolated from thermophile Aspergillus terreus, which can restore drug sensitivity and could be the key to improve breast cancer therapeutics." (PMID 28330151, 2016). "In breast cancer cells, trans-chalcone and licochalcone A decreased ABCC1 expression in MCF-7 cells and downregulated ABCG2 (but not ABCC1) in BT-20 cells." (PMID 40362377, 2025). "While each laboratory reporting ABCG2 had their own noncanonical name, the common name for ABCG2 was breast cancer resistance protein (BCRP), alluding to its discovery from a drug-resistant breast cancer cell line." (PMID 37438132, 2023). "Some studies have suggested that SALL4 silencing in Dox BC resistance cell lines reverts the resistance through cell cycle arrest and downregulation of membrane transporter ABCG2, more commonly referred to as BCRP (breast cancer resistance protein) and nuclear receptor-binding protein 1 (NRBP1)." (PMID 36362083, 2022). "VEGFA is also known to modulate cancer stem cell-enriched side population in breast cancer patients through non-canonical PKA/β-catenin pathway and ABCG2/ABCB1 drug efflux transporters." (PMID 35884426, 2022). "A few papers indicate that hypermethylation of the ABCB1 promoter is a frequent event in breast cancer, so far data on promoter methylation of ABCC1 and ABCG2 has, however, not been published." (PMID 27689338, 2016). "In contrast, topotecan, a bona fide transport substrate of ABCG2, accumulated exclusively in EVs of MDR cells but was neither detected in lysosomes of normal breast epithelial cells nor in non-MDR breast cancer cells." (PMID 22530032, 2012). "The role of ABCG2 in OSCC is not known, and there are few studies in the available literature that have analyzed this role, mainly due to the resistance of OSCC to chemotherapy, following the findings related to breast cancer." (PMID 36982894, 2023). "At the marker profile, the Quiescent stem-like population expresses the pluripotency markers, while the Progenitor population in breast cancer cells can be marked by CD44 with diminished pluripotency markers and without other CSC markers like ALDH1A1/3 or ABCG2." (PMID 34150761, 2021). "Specifically, CD147 can increase ABCG2 protein expression, but not mRNA expression, and affect the cellular localization and dimerization of ABCG2, thereby regulating its drug transporter function in MCF-7 breast cancer cells." (PMID 25268615, 2014).
breast cancer (continued). "However, they are not BCRP substrates, since there are not different growth inhibitory effects for these compounds on ABCG2-overexpressing (MDA-MB-231/R) and parental (MDA-MB-231/V) breast cancer cells." (PMID 30096910, 2018).
gout (205 papers, 2009 to 2026). A condition characterized by painful swelling of the joints, which is caused by deposition of urate crystals. "SLC2A9 and ABCG2 are major genetic loci associated with uric acid and gout across multiple ancestral populations." (PMID 41311848, 2025). "ABCG2 polymorphisms: Associated with both increased gout susceptibility and poorer response to certain urate-lowering therapies, particularly in young-onset disease." (PMID 41329531, 2025). "A cross-ancestry meta-analysis of GWAS cohorts of European (EUR) or East Asian (EAS) descent identified single-nucleotide polymorphisms (SNPs) in SLC2A9 (uric acid: rs3775948; gout: rs4697701) and ABCG2 (gout: rs2622621) at single-variant resolution." (PMID 41311848, 2025). "Common dysfunctional variants (polymorphisms) in the ABCG2/BCRP gene are major genetic causes of gout/hyperuricemia." (PMID 41452549, 2025). "The strong signal at this locus reinforces the importance of ABCG2 in the pathophysiology of gout again, as it encodes a transporter protein that plays a key role in the uric acid efflux transport." (PMID 41075270, 2025). "How do host genetics (e.g., ABCG2 polymorphisms, HLA-B*5801) interact with microbiota composition to modify gout susceptibility and severity?" (PMID 41583434, 2025). "The ABCG2 gene was highly associated with uric acid levels (P = 2.24 × 10−92), confirming its role in gout susceptibility." (PMID 41075270, 2025). "Cross-ancestry fine-mapping has identified ancestral and functional variants in SLC2A9 or ABCG2 that exhibit primate-specific regulatory effects on uric acid and gout." (PMID 41311848, 2025). "Dysfunctional variants of ABCG2 can lead to reduced uric acid excretion, thereby contributing to hyperuricemia, a major risk factor for gout." (PMID 41075270, 2025). "ABCG2 plays a pivotal role in the transport of sterol sulfate and urate, with deficiency of ABCG2 function being a major contributor to hyperuricemia and gout." (PMID 38397468, 2024). "Along this view, any factors, including genetic or attained factors that alter the optimal ratio between NUMB and ABCG2 would potentially cause hyperuricemia and gout." (PMID 39433541, 2024). "Leveraging its improved power, FABIO successfully prioritized multiple potentially causal genes associated with the diseases, including GATA3 for asthma, ABCG2 for gout, and SH2B3 for hypertension." (PMID 39621803, 2024). "GWAS and epidemiological studies identified several genes associated with gout, including the two most prominent urate transporters (ABCG2 and SLC2A9)." (PMID 38397902, 2024). "A common polymorphism (rs2231142, Q141K) in ABCG2 was identified to be associated with gout and gout related symptoms such as serum urate concentration in previous GWAS and our GWAS analysis." (PMID 39621803, 2024). "It has been revealed that 88.2% of patients who develop gout at the age of 20 or younger have mutations in the uric acid excretion transporter ABCG2 gene." (PMID 39024316, 2024). "Previous GWAS using participants with gout and asymptomatic hyperuricemia detected the loci of genes encoding urate transporters (ABCG2 and SLC2A9) as genetic factors aggravating normouricemia into gout." (PMID 38397902, 2024). "ABCG2 functional polymorphisms were associated with higher gout susceptibility and a clinically severe, early onset disease." (PMID 35939175, 2023). "Previous reports have identified an association between ABCG2 and hyperuricemia and susceptibility to gout, with another known ABCG2 missense variant of the ABCG2 gene (rs2231142)." (PMID 37425708, 2023). "Nonsynonymous allelic variants of ABCG2 were shown to significantly hasten the onset of hyperuricemia and increase the likelihood of gout and the presence of a family history of gout." (PMID 37238926, 2023).
gout (continued). "In genome-wide association studies (GWAS), the strong association of the ABCG2 rs2231142 variant with gout that is mediated by both decreased intestinal urate excretion and renal overload hyperuricemia was confirmed in the Asian population." (PMID 36967798, 2023). "The ABCG2 rs2231142 variants not only lead from hyperuricemia to gouty arthropathy, but also increase the risk of incident nephrolithiasis." (PMID 36967798, 2023). "Our results demonstrate that patients with ABCG2 functional polymorphisms presented gout approximately 8 years earlier than wild type gouty patients, on average at the age of 37.6." (PMID 35939175, 2023). "A study on Chinese patients revealed that the epistatic interactions between PKD2 and ABCG2 affect serum urate concentration and gout risk." (PMID 38060535, 2023). "ABCG2 dysfunction indeed hastened gout onset but was also significantly associated with later PD onset." (PMID 38137389, 2023). "The ABCG2 rs2231142 genotype has a strong association with hyperuricemia and gout through the mechanisms of both decreased intestinal urate excretion and renal overload in the Asian population." (PMID 36967798, 2023). "The paper also highlighted relations between ABCG2 SNPs, gout susceptibility and disease severity characterised by an early onset disease with frequent flares and tophi formation." (PMID 35939175, 2023). "In conclusion, this study found, for the first time, that rs1481012 of ABCG2 was associated with the risk of gout in Koreans." (PMID 38060535, 2023). "In previous studies, rs1481012 in ABCG2 has been associated with risk of hyperuricemia, gout, coronary artery disease (CAD), B-cell non-Hodgkin lymphoma (B-NHL), and chronic lymphocytic leukemia (CLL)." (PMID 38060535, 2023). "Rs2728121 in PKD2 and rs1481012 in ABCG2 affect the etiology of diseases and are associated with elevated serum urate, hyperuricemia, and gout, which was in agreement with our findings that rs1481012 affects gout." (PMID 38060535, 2023). "The single nucleotide polymorphism of ABCG2 causes reduced extrarenal excretion type hyperuricemia and gout; amino acid substitution Q126X abolishes ABCG2 function completely, whereas Q141K reduces it by 25%." (PMID 37238929, 2023). "Even in the presence of ABCG2 pathogenic mutations, these mutations still have a protective effect on gout." (PMID 35922835, 2022). "We performed a large GWAS to explore the genetic variants and PRS relating to gout and AH in males, and we found that the variants located in genes ABCG2 and SLC2A9 were the major genetic factors governing gouty attack and hyperuricemia." (PMID 36221101, 2022). "Specially, gene-sex interaction exists for ABCG2, with effect allele exerting greater influence on gout risk in men than women." (PMID 34986901, 2022). "Meanwhile, ABCG2 is identified as a physiological important uric acid transporter, and its dysfunction can increase the risk of gout and hyperuricemia." (PMID 35959356, 2022). "Its variants can lead to destabilization of the nucleotide-binding structural domain of ABCG2, resulting in its reduced expression and dysfunction, leading to the inadequate renal excretion of urate, causing hyperuricemia and gout." (PMID 35813212, 2022). "Overall, the genetic polymorphism rs2231142 (G > T) in the ABCG2 gene is considered the most significant genetic polymorphism in developing HU or gout in multiple populations compared with other uric acid risk alleles." (PMID 34986901, 2022). "ABCG2 is located on chromosome 4q, as identified by genome-wide association studies related to hyperuricemia and gout." (PMID 36483739, 2022). "ABCG2 variants (rs2231142) are variants associated with gout and an increased frequency of erythema." (PMID 35813212, 2022). "ABCG2 gene is located at the gout susceptibility site of chromosome 4q, and expressed on the apical membrane of cells in various tissues such as the intestine, liver and kidneys." (PMID 35281005, 2022).
gout (continued). "The genetic polymorphism rs22131142 (G > T) in ABCG2 is significantly associated with a higher risk for HU and gout among different populations." (PMID 34986901, 2022). "Individuals carrying the ABCG2 SNP (rs2231142) have a nearly 2-fold increased susceptibility to gout, and alcohol consumption independently increases the risk of gout stones in the Han Chinese population in Taiwan." (PMID 35813212, 2022). "The ABCG2 SNP (rs72552713) also significantly increased the risk of gout in Asians (dominant model: OR = 3.87, 95% CI = 2.07–7.24, p = 0.06 for heterogeneity)." (PMID 35813212, 2022). "While genetic polymorphism in ABCG2 increases the risk for developing gout in the population at large, genetic polymorphism in ABCG2 exerts different effect sizes between sexes." (PMID 34986901, 2022). "Genetic polymorphisms in the ABCG2 were reported to contribute to elevated urate levels leading to HU and gout." (PMID 34986901, 2022). "The naturally occurring Q141K and M71V polymorphisms in ABCG2, associated with gout and hyperuricemia, affect the cellular routing of the transporter, rather than its transport function." (PMID 33634118, 2021). "First, for high-risk patients with the ABCG2 rs2231142 risk T allele, body weight control and reduction in BMI are recommended to prevent hyperuricemia and possibly avoid development of gouty arthritis as well as associated comorbidities." (PMID 34531894, 2021). "We previously reported that ABCG2 (ATP-binding cassette subfamily G member 2) is a renal and intestinal urate exporter and that its dysfunctional variants have a significant and strong effect on susceptibility to gout/hyperuricemia." (PMID 33517564, 2021). "Among these, solute carrier family 2 (SLC2A9) and ATP-binding cassette superfamily G member 2 (ABCG2) have multiple variants associated with serum urate levels and, overall, the increased risk of gout." (PMID 33926105, 2021). "The single nucleotide polymorphism ABCG2 rs2231142 is strongly associated with early-onset gout in Polynesian, Japanese, Czech, and other European populations." (PMID 34207250, 2021). "In a Taiwanese cohort study, ABCG2 rs2231142 was associated with tophaceous gout across the alcohol consumption, with a stronger association in everdrinkers (OR = 25.05) than in current drinkers (OR = 12.69)." (PMID 34834509, 2021). "Based on a positive family history of hyperuricemia or gout, we identified two rare mutations, c.393G>T (p.M131I) and c.706C>T (p.R236X), in the ABCG2 gene." (PMID 33669292, 2021). "A missense single nucleotide polymorphism (SNP) in ABCG2 (rs2231142; Q141K) has been shown to be associated with urate concentrations and gout in both white and black individuals." (PMID 34144706, 2021). "The ABCG2 gene is strongly associated with SU levels, early-onset gout, and the progression from HU to gout." (PMID 33810064, 2021). "In conclusion, we found a representative case of pediatric hyperuricemia with familial gout that harbored two dysfunctional ABCG2 mutations." (PMID 33669292, 2021). "ABCG2 genetic variants have been reported to be associated with reduced efficacy of drug treatments and risks of diseases, such as gout, Alzheimer’s disease, and isolated septal defects." (PMID 34680995, 2021). "We describe a representative case of familial pediatric-onset hyperuricemia and early-onset gout associated with a dysfunctional ABCG2, i.e., a clinical history of three generations of one Czech family with biochemical and molecular genetic findings." (PMID 33669292, 2021).
gout (continued). "ABCG2 encodes a high-capacity urate efflux transporter, located in a gout-susceptibility locus (MIM 138900) on chromosome 4q, and some genetic variants can increase uric acid levels." (PMID 34834509, 2021). "Among these, especially SNPs of ABCG2 have been highly associated with pediatric-onset hyperuricemia and early-onset gout." (PMID 34206432, 2021). "The ABCG2 gene is a well-established hyperuricemia/gout risk locus encoding a urate transporter that plays a crucial role in renal and intestinal urate excretion." (PMID 33669292, 2021). "The odds ratios of gout risk were 2.80 (p=0.001), 4.56 (p<0.001), and 7.67 (p=0.002) for Caucasian, Mongoloid, and Polynesian populations carrying the ABCG2 rs2231142 TT genotype, respectively, compared with the GG genotype." (PMID 34531894, 2021). "Common defects of the ABCG2 exporter have been identified to cause elevated serum uric acid and gout." (PMID 34639563, 2021). "SLC2A9 is the most frequently reported gene associated with SUA levels, along with ABCG2, in GWAS studies of hyperuricemia and gout." (PMID 34572357, 2021). "Genome-wide association (GWA) studies have shown that decreased expression level and/or function of ABCG2 are associated with elevated serum uric acid levels, an important risk factor for gout development." (PMID 34855903, 2021). "ABCG2 gene mutation has a significant effect on UA, especially the amino acid substitution in Q141K, which leads to risk of hyperuricaemia and gout." (PMID 34335246, 2021). "Collectively, the genetic polymorphism rs2231142 (G > T) in ABCG2 is believed to be the most significant gene variant associated with HU and gout compared to other risk alleles." (PMID 33810064, 2021). "Several other ABCG2 mutations/polymorphisms have been identified as genetically associated risk factors for gout incidence." (PMID 33801813, 2021). "Dysfunction of URAT1 and GLUT9 reportedly cause inherited hypouricemia type 1 and type 2, respectively, while dysfunction of ABCG2 is a risk factor for hyperuricemia and gout." (PMID 33669292, 2021). "The genetic polymorphism rs2231142 (G > T) in ABCG2 is strongly associated with increased risk for HU and gout across different populations." (PMID 33810064, 2021). "Because of its frequency and its association with gout (see Section 6.1), ABCG2-Q141K is the most broadly studied variant of ABCG2." (PMID 33801813, 2021). "A minor allele of p.V12M appears to be protective regarding susceptibility to gout; however, this apparent effect is due to linkage disequilibrium between p.V12M and other dysfunctional ABCG2 variants." (PMID 33669292, 2021). "Genome-wide association studies (GWAS) revealed that one of the common single nucleotide polymorphisms (SNP), ABCG2-Q141K, is strongly associated with higher serum urate levels and gout." (PMID 31254042, 2020). "ABCG2 is a high-capacity urate exporter in the kidney and intestine, the dysfunction of which increases the risk for gout and hyperuricemia." (PMID 32180207, 2020). "For ABCG2, rs2231142 significantly increased risk of gout by about 2 to 4 times and 1.6 to 3 times in Asians and Caucasians respectively for carrying heterozygous and homozygous minor genotypes." (PMID 33087043, 2020).